SPP1 (secreted phosphoprotein 1)
Diseases named in the same sentence as SPP1 in open-access papers (continued):
Sharing a sentence is not in itself a finding about the gene and the disease.
tumor (continued). "A low CS ratio (SPP1-dominant) correlates with hypoxia-driven metabolic reprogramming, EMT, and diminished cytotoxic immune infiltration, fostering tumor progression and therapy resistance." (PMID 41391064, 2025). "High-dimensional, multi-omic analysis of patient samples reveals a higher frequency of exhausted tumor-reactive CD8+ T cells and enriched interactions between these cells and SPP1+ macrophages in profibrotic, alpha-SMA rich regions specifically in the liver." (PMID 40335453, 2025). "In vitro studies indicate that SPP1 + TAMs secrete SPP1, CCL18, and CXCL8, all of which enhance tumor invasion and metastatic potential." (PMID 41391064, 2025). "Key pathways involved include MDK, PTN, SPP1, and FN1, all of which play central roles in immune regulation and tumor progression." (PMID 40837013, 2025). "Conversely, a remarkably immunosuppressive tumor microenvironment (TME) is detected in LM, characterized by lymphocyte depletion and a concurrent enrichment of SPP1+ macrophages, compared to BM." (PMID 40883281, 2025). "The tumor cells were further subgroup into tumor high and tumor low utilizing the GLMscore formula, the SPP1+ and CCL20+ macrophages shared elevated intercellular communications with tumor high cells." (PMID 40443528, 2025). "PPI analysis revealed COL10A1, POSTN, SPP1, MMP11, and GREM1 as key hub genes in extracellular matrix (ECM) remodeling and tumor progression." (PMID 40826767, 2025). "Currently, TREM2 (triggering receptor expressed on myeloid cells 2)+ TAMs drive tumor progression and immunotherapy resistance in HCC through SPP1-mediated effects on both cancer cells and CD8+ T cells." (PMID 41225975, 2025). "Further research indicated that inhibition of SPP1 effectively decreases N‐cadherin and β‐catenin expression, simultaneously blocking AKT and STAT3 activation and significantly reducing tumor cell invasion and metastasis." (PMID 40356222, 2025). "They observed enriched SPP1+ TAMs in chemotherapy‐resistant patients, suggesting SPP1+ TAMs directly interact with CD44 on tumour cells to promote chemoresistance." (PMID 40954554, 2025). "Increased CDC20, LPCAT1, and SPP1 and reduced PON1 were found in tumor tissues than normal tissues, as well as in advanced patients than early-stage patients." (PMID 40404896, 2025). "The results of TCGA-LIHC dataset analysis showed that compared with normal tissues, CDC20, LPCAT1, and SPP1 were significantly up-regulated and PON1 was significantly down-regulated in tumor tissues." (PMID 40404896, 2025). "Interactions of SPP1+ TAMs were also examined in another study of CRC, where the SPP1+ TAMs were found to exhibit interactions with tumour cells via the binding of SPP1 and CD44 on tumour cells." (PMID 40954554, 2025). "Despite these differences, we believe the genes identified in our study—COL3A1, PLAU, and SPP1—have common roles in ECM remodeling, cell adhesion, and tumor cell migration, processes that are shared across cancer types." (PMID 41465316, 2025). "Our findings revealed a pronounced elevation of SPP1+ macrophages in CRC, especially within tumor territories." (PMID 40092488, 2025). "VARGG accurately reveals the spatial organization of tumors and identifies key genes related to tumor progression and immune microenvironment (VEGFA, CD74, SPP1, IGFBP5, TIMP2, EMP1, THY1)." (PMID 41275376, 2025). "Our recent study demonstrates that macrophage-derived SPP1 critically impairs CD8+ T cell infiltration into the tumor microenvironment (TME), thereby accelerating tumor progression and diminishing the efficacy of immune checkpoint inhibitor (ICI) therapy." (PMID 41425545, 2025). "SPP1 is a potent chemotactic factor for macrophages, facilitating their recruitment into the TME and reprogramming them into tumor-supportive phenotypes." (PMID 41391064, 2025).
tumor (continued). "Our results showed that MED6-positive tumor cells exhibited more significant activity in interactions with stromal and immune cells via secreted signals like SEMA, MDK, and SPP1." (PMID 40302793, 2025). "We observed a positive correlation between a higher C1QC: SPP1 TAM ratio and macrophage phenotype and tumor T cell density." (PMID 41415295, 2025). "Of note, JUNB performs tumour suppressor activity in NLPHL, supporting its regulatory connection with SPP1 restricted to cHL." (PMID 40149711, 2025). "We found that these SPP1 positive myeloid cells (Macro_SPP1/CCL3 and Macro_SPP1) resembled the pro-tumor macrophages in a CXCL9-SPP1 macrophage polarity system, a new human cancer dataset based classifying system to replace M1-M232." (PMID 40883281, 2025). "SPP1 (secreted phosphoprotein 1), also known as osteopontin, interacts with CD44 to promote tumor growth, metastasis, and immune evasion." (PMID 39955556, 2025). "TC tumor cells expressed receptors for multiple signaling pathways, including MK, PTN, SPP1, TWEAK, EGF, and IFN-II (IFNG) (blue frames)." (PMID 41228323, 2025). "The recruited neutrophils were activated by SPP1 and then formed NETs-dominant PMN to trap the disseminated tumor cells and promote metastatic colonization." (PMID 39529085, 2024). "Specifically, in the MIF, MK, and SPP1 signaling pathways, high-DRS tumor cells acted as key senders and influencers communicating with immune cells." (PMID 38862242, 2024). "Altogether, these studies highlight the role of SPP1+ TAM in pro-tumor fibrosis; we further describe the functions of these cells in regard to their relationship with fibroblasts and tumor cells." (PMID 39075108, 2024). "Dysfunctional T cell subgroups (characterised by T cell exhaustion), immunosuppressive myeloid subgroups marked by SPP1, PDCD1, or TERM2, and fibroblasts have been observed at the tumour boundary." (PMID 39350478, 2024). "CTShigh and C1Qhigh TAMs generate immunosuppressive interactions with aDTCs via predominantly secretion of SPP1, FN1, TIMP1, or upregulation of CD74, all of which foster tumor-cell metastasis." (PMID 38460015, 2024). "Differential expression analysis between macrophages from the tumor and normal tissue identified genes that are enriched specifically within TAMs (TREM2, GPR84 and SPP1) and tissue-resident macrophages (LYVE1), which is consistent with previous observation." (PMID 38349405, 2024). "In the realm of SPP1 signaling, MSA-2 strikingly consolidated communications between T cells and macrophages/monocytes/tumor cells, particularly tumor cells." (PMID 38550593, 2024). "The LGALS3/JUN/ITGB1/SPP1 genes were highly expressed in MES-like GBM cells, and the expression of these genes was significantly upregulated with tumour progression." (PMID 39629136, 2024). "Another subcluster enriched in tumor tissue is SPP1+ TAMs, which regulate the functional state of TIME and tumor angiogenesis, thereby promoting tumor progression." (PMID 38649887, 2024). "In HCC, SPP1 signals can crosstalk with the colony-stimulating factor-1 (CSF1) pathway to mediate the TME switch from Th1 to Th2, which is vital for tumor progression." (PMID 39616302, 2024). "Tumor-promoting and anti-inflammatory factors TGF β, IL10 and VEGF were significantly stimulated by rh SPP1 protein but inhibited by anti-SPP1 antibody." (PMID 38648200, 2024). "A specific TAM subset, SPP1+ TAMs, colocalized with CAFs in the TME, contribute to the immune escape of tumour cells." (PMID 38303024, 2024). "Both in vitro and in vivo experiments and the use of VGX-1027, an inhibitor of macrophage-derived TNF-α and IL-1β, confirmed that SPP1 + Mac-derived TNF-α and IL-1β promoted HNSCC progression by supporting tumor cell proliferation and migration." (PMID 39726047, 2024).
tumor (continued). "We observed that macrophages nearer the central tumor region expressed higher levels of SPP1 and lower levels of MMP12, while macrophages closer to the peripheral tumor region exhibited the opposite expression pattern of SPP1 and MMP12." (PMID 39764138, 2024). "SPP1, or osteopontin, was found able to guide EMT through multiple cellular signaling pathways and by restructuring the tumor microenvironment to modify EMT processes." (PMID 38987572, 2024). "We compared proportions of each myeloid subtype in each patient, finding that SPP1+APOE+ TAM (Diff = 9.5%, p = 0.011) and CD62L+IFN-high neutrophils (Diff = 5.0%, p = 0.046) were significantly enriched in primary tumor patients versus adjacent normal." (PMID 39075108, 2024). "Briefly, SPP1 + Mac-derived TNF-α and IL-1β promote the expression of OPN in both macrophages and tumor cells." (PMID 39726047, 2024). "To further confirm the interactive SPP1/ITGB1 signaling between TAMs and tumor cells, we conducted QIF analysis on another independent cohort involving 105 tumor tissue samples." (PMID 39207055, 2024). "Through in vitro studies, we also found that SPP1 mediated interactions between TAM clusters and between TAM and tumor cells." (PMID 38648200, 2024). "In this study, we identified a different regulatory way by which SPP1 + Macs released the cytokines TNF-α and IL-1β to promote tumor progression." (PMID 39726047, 2024). "In the present study, both SPP1+ Mac and SELENOP+ Mac in MLN were found to promote tumor cell growth and were significantly increased in MLN." (PMID 38755647, 2024). "This enrichment was also observed in tumor-specific SPP1+ macrophages (Tumor_specific_SPP1+_macrophages_UP, NES = 2.5, p adj < 0.001) as well as in the Spp1+ LAM subset identified in the GSE227088 dataset (GSE227088 Spp1_LAM_UP, NES = 2.2, p adj < 0.001)." (PMID 38449872, 2024). "We discovered L-R pairs in both the SPP1 and ANGPTL signaling pathways, and determined that the related genes were considerably elevated in tumor cells." (PMID 38191424, 2024). "SPP1, a pro-metastatic protein, has been widely studied and is closely related to immune escape, EMT, and other functions required for tumor metastasis." (PMID 39529085, 2024). "Furthermore, single-cell RNA-seq analysis demonstrated that SPP1 controlled the interaction between HCC cells and macrophages through SPP1/CD44 and SPP1-PTGER4 signaling, and in vitro data also showed that SPP1 induced the polarization of macrophages to M2-like tumor-associated macrophages (TAMs)." (PMID 38919629, 2024). "Inhibition of SPP1 attenuated N-cadherin and β-catenin expression and the activation of AKT and STAT3 pathway in tumor cells." (PMID 38648200, 2024). "By contrast, highly expressed genes in cluster I10 included multiple known pro-tumor markers in macrophages, such as TREM2, CX3CR1, and SPP1." (PMID 38167466, 2024). "We identified a novel subset of macrophages that, through secretion of SPP1, bind to CD44 on tumour cells, activating the PDE3B pathway via the integrin enzyme pathway, thereby inducing chemotherapy resistance in TNBC patients." (PMID 38982317, 2024). "Ye and colleagues' spatial omics analysis has identified the enrichment of SPP1+ macrophages at the borders of colorectal and liver cancers, where they engage in complex crosstalk with adjacent ASPN+/FAP+ fibroblasts and tumour cells." (PMID 39350478, 2024). "TIB is formed by the interaction of SPP1+ macrophages and CAF, which limits the immune cell infiltration of tumor core." (PMID 39085965, 2024). "For SPP1+ macrophages, the activation of the SPP1-CD44 axis promotes the stemness of the tumor cells, contributing to tumor metastasis in pancreatic cancer." (PMID 38600248, 2024). "SPP1 bound with integrins such as ITGB1 and ITGB5, implying the role of SPP1 in integrin signaling between fibroblasts, macrophages, and tumor cells that lead to EMT and cell-adhesion to the ECM." (PMID 39075108, 2024).
tumor (continued). "Survival analysis of CTHRC1 and SPP1 gene expression in PAAD demonstrated that patients with high expression of these genes led to worse survival, demonstrating the pro-tumor functions of these genes in the clinical context." (PMID 39075108, 2024). "Amongst them, two genes connected to lactate, namely secreted phosphoprotein 1 (SPP1) and MYC proto-oncogene (MYC), are significantly increased by more than four times in the tumor samples." (PMID 38397058, 2024). "The third and the most important discovery was the reprogramming role of cellular interaction between SPP1+ macrophages and POSTN+ fibroblasts and tumor cells, thus reshaping the desmoplastic TME." (PMID 38519500, 2024). "The interaction between SPP1 and CD44 is thought to inhibit the activation of CD8 + T cells, promoting tumor immune tolerance and immune escape." (PMID 38806553, 2024). "The expression of CXCL9 and SPP1 was employed to define TAM polarization, characterizing their roles in tumor promotion or suppression." (PMID 38222314, 2024). "High-dimensional, multi-omic analysis combining proteomic CODEX and scRNA-seq data revealed enriched interaction of SPP1+ macrophages and CD8+ tumor-reactive T cells in profibrotic, alpha-SMA rich regions in the liver." (PMID 39372792, 2024). "Subsequently, we found that Spp1+ macrophages promote TAS CD8+ T cell exhaustion and dysfunction affecting tumor burden." (PMID 39372792, 2024). "Further cell‐cell communication analysis using CellChat revealed the strongest interaction between SPP1+ TAM and ITGB1high tumor cells." (PMID 39207055, 2024). "Reports have indicated that SPP1+ TAM promote angiogenesis in HNSCC and enhance tumor infiltration and metastasis through the upregulation of cytokine expression." (PMID 39234254, 2024). "Previous studies showed that SPP1-CD44 and SPP1-PTGER4 interacted actively with immune cells and mediated crosstalk between tumor cells and macrophages and our study also found that macrophage-to-epithelial cell crosstalk via SPP1-CD44 was also a validation." (PMID 38648200, 2024). "SPP1 promoted the tumor-promoting ability of TAM, and increased PDL1 expression and stemness of tumor cells." (PMID 38648200, 2024). "Spatial heatmaps of SPP1 and CD163 confirm the localization of the expression of these genes in, respectively, the tumor and healthy regions of the tissue." (PMID 38217002, 2024). "Previous studies indicated that the SPP1 plasma levels were influenced by Edmondson grading, TNM staging and the number of tumor nodules of HCC patients, which made plasma SPP1 levels vary from patient to patient in the same group." (PMID 39529085, 2024). "Further, AGTR1 is also involved in regulating immune chemokines, checkpoints and immune regulatory factors such as PECAM1, ADARB1, SPP1 and ENO1, all of them playing important roles in immune cell regulation, tumor cell proliferation and migration." (PMID 39450258, 2024). "Conversely, miR422a-3p exhibited an inverse relationship with the expression of SPP1 and FOXD1-AS1 in tumor cells isolated from primary PC tissues." (PMID 38167126, 2024). "To investigate the spatial connection of SPP1 + SIRPα + macrophages with tumor cells and CD8 + T cells, we conducted in-situ mIHC staining in 39 ESCC patients from ESCC cohort 1 using antibodies against CD68, SIRPα, SPP1, panCK, PD-1, and CD8." (PMID 39696410, 2024). "Thus, we hypothesize that the secretion of SPP1 in regulating the HCC tumor microenvironment may be a mechanism underlying the malignant functions of KHDRBS1-positive cells, as the role of SPP1 in remodeling the tumor microenvironment has been widely reported in various cancers." (PMID 38660302, 2024). "Moreover, tumor expression of CD44, a hallmark of cancer cell “stemness” that promotes tumor survival and proliferation, was upregulated in refractory patients and depleted in the responsive ones, with higher stromal expression of one of its ligands, SPP1, in the responsive group." (PMID 38064127, 2024).
tumor (continued). "SPP1+ macrophages attract regulatory T (Treg) and CD8+ T cells into CRC tissues, leading to anti-tumor immune resistance and depletion of CD8+ T cells." (PMID 38646539, 2024). "Here, we applied scRNA-seq to determine the differences in myeloid cells between adjacent normal tissues and tumor tissues from HNSCC patients and identified SPP1 + Macs as a crucial subtype of macrophages in HNSCC." (PMID 39726047, 2024). "Detailed analysis of macrophage-related signaling pathways revealed an increase in the activity of SPP1 and MIF pathways in tumors, potentially related to macrophages promoting tumor growth, invasion, or immune suppression (left)." (PMID 39850883, 2024). "Ligand-receptor analysis between macrophages and tumor cells identify C5/C5AR1,SPP1/ITGA4, and TF/TFRC as the ligand-receptor signaling mechanism driving these niche-DE genes." (PMID 38217002, 2024). "For instance, the interaction between the glycoprotein SPP1 and the cell surface receptor CD44 has been found to inhibit T cell activation and proliferation, as well as promote tumor immune evasion." (PMID 38515213, 2024). "OPN+ (SPP1+) macrophages, a subtype of TAM with a distinct feature, was recently shown to possess immunosuppressive properties and positively correlate with tumor growth and metastasis." (PMID 39062100, 2024). "Compared to normal tissues, the tumor group exhibited a higher abundance of Macro-FOLR2, Macro-SPP1 and cDC-FCER1A, with a lower proportion of Mono-FCN1." (PMID 39093451, 2024). "Based on our findings, we observed that PLOD2 + SAA1 + tumor cells were able to communicate with TME cells and act as strong senders and influencers in signaling pathways such as SPP1, MIF, PTN, and MK." (PMID 38951896, 2024). "We found that signals such as SPP1 and MIF were more active in tumor tissues, indicating potential oncogenic roles of macrophages." (PMID 39850883, 2024). "By in vitro study, we showed SPP1 mediated the interactions between TAM clusters and between TAM and tumor cells." (PMID 38648200, 2024). "On the other hand, the expression of SPP1 was increased only in MIBC (by 1.4-fold), and the mRNA level of S1PL1 was significantly higher (by 1.5-fold) in MIBC neoplasms, compared to NMIBC." (PMID 39595959, 2024). "Our results highlighted that SPP1+ cells also exhibited a signature of inhibiting immune cell infiltration, suggesting an immunosuppressive and tumor escape role in the TNBC tumor microenvironment." (PMID 39440065, 2024). "Protumorigenic factors associated with hypoxia and angiogenesis, like HIF1A and VEGFA, as well as genes related to a pro-tumoral phenotype, such as SPP1 and TGFB2, were highly expressed in this macrophage found in the tumor context." (PMID 38972873, 2024). "Ten signaling pathways only existed in the lymphatic metastases, including CD22, CD45, IL16, SPP1, LIGHT, ANGPTL, GRN, ncWNT, PERIOSTIN, and NEGR, in addition to the classical ncWNT pathways that can promote tumor progression." (PMID 37221625, 2023). "Key subtype markers, SPP1 and S100P, were mapped across the UMAP plot to obtain valuable insights into their differential expression and potential roles in tumor progression." (PMID 38239853, 2023). "Gene expression levels of ANXA1-FPR3, NECTIN2-TIGIT, CXCL8-NR3C1, LGALS9-HAVCR2, C5AR1-RPS19, and SPP1-PTGER4 pairs were higher in sender and receiver cells derived from tumor tissue compared with normal tissue." (PMID 38002057, 2023). "The S100A12+, ISG15+ and TXNIP+ subtypes are found in peripheral blood, the ELL2+ and PTGS2+ mainly in adjacent liver and the MMP8+, APOA2+, CD74+, IFIT1+, SPP1+ and CCL4+ predominantly located in the tumour." (PMID 37534829, 2023). "The six HCC TAN clusters; MMP8+, APOA2+, CD74+, IFIT1+, SPP1+ and CCL4+ can be characterised by predicted function and role in tumour development." (PMID 37534829, 2023). "Compared with OBs, CSC-like cells overexpressed SPP1 and SERPINA1 genes related to tumor progression." (PMID 36588108, 2023).